BCL2 (BCL2 apoptosis regulator)
Diseases named in the same sentence as BCL2 in open-access papers (continued):
Sharing a sentence is not in itself a finding about the gene and the disease.
ovarian carcinoma (continued). "We observed that the expression of Bcl-2 was significantly up-regulated by sevoflurane, whereas the expression of Bax and cleaved Caspase3 was down-regulated, indicating that sevoflurane promotes cell apoptosis in ovarian cancer through regulating the Bcl-2/Bax axis and Caspase cascade." (PMID 31889892, 2019). "Additionally, BCL2L2 was found overexpressed in ovarian cancer cells, which had been also reported in a study of Li et al14 on the relationship between miRNA‐21 and Bcl‐2 where Bcl‐2 protein expression is drastically upregulated in ovarian cancer cells in comparison with normal ovarian tissues." (PMID 30019389, 2018). "Therefore, targeting Bcl-2 may provide an effective therapeutic method to solve drug resistance in ovarian cancer." (PMID 30454003, 2018). "However, it may be useful in the small fraction of ovarian cancer patients that express high levels of Bcl-2." (PMID 27080533, 2016). "Thus, in the present study, we investigated whether TW-37-induced inhibition of epithelial ovarian cancer growth could be attributed to Bcl-2 inactivation in vitro, and whether TW-37 increased the sensitivity of ovarian cancer cells to DDP." (PMID 25823945, 2015). "Consistent with our hypothesis, it was recently shown that the Src/Abl kinases inhibitor Dasatinib arrested the growth of ovarian cancer xenograft by inducing BECLIN 1-dependent autophagic cell death, and hyperstimulation of autophagy was associated with downregulation of BCL-2 expression." (PMID 25136588, 2014). "Clinical validation of urinary Bcl-2 as a reliable biomarker for ovarian cancer was conducted with ELISA tests using urine samples collected from 388 patients, including healthy controls and patients with benign gynecological disorders, early- and late-stage ovarian cancer." (PMID 22969352, 2012). "Based on enzyme-linked immunosorbent assay (ELISA) tests using urine samples, the average urinary level of Bcl-2 was found to be 0.59 ng/mL in healthy patients, 1.12 ng/mL in benign disorders, 2.60 ng/mL in early-stage ovarian cancer and 3.58 ng/mL in late-stage ovarian cancer." (PMID 23112714, 2012). "Clearly, then, further studies with additional samples are warranted since, the combination of Bcl-2 expression and lymphocyte status may be important for prognostic outcome or provide useful targets for therapeutic intervention in patients with epithelial ovarian cancer." (PMID 19852858, 2009). "Resveratrol reverses ovarian cancer doxorubicin‐resistant status by suppressing MDR1, MRP1, and Bcl‐2 gene expression levels." (PMID 40968783, 2026). "HAGLROS is an upregulated lncRNA in ovarian cancer cells; HAGLROS knockdown increases apoptosis rate, upregulates BAX protein expression, and downregulates BCL-2 protein expression via the HAGLROS/miR-26b-5p axis (Zhu and Mei, 2021)." (PMID 39967908, 2025). "In ovarian cancer (IOSE144, A2780, OVCAR3, and SK-OV-3) cells, dihydroartemisinin downregulates Bcl-2 and upregulates Bax, which inhibits cancer cell proliferation and leads to cell cycle arrest at the S phase." (PMID 40490812, 2025). "These researchers further observed decreased expression of HOTAIR, bcl-2, and H19, along with overexpression of MEG3, after treating ovarian cancer cells with DNC, indicating that curcumin exerts its anticancer effects via multiple pathways." (PMID 39830662, 2024). "In preclinical ovarian cancer models, ASA treatment determined a significant reduction in Bcl-2 protein level with concomitant increase in caspase 3, revealing its antitumor and antiangiogenic effects." (PMID 39021835, 2024).
ovarian carcinoma (continued). "Navitoclax is a small-molecule inhibitor of the Bcl-2 family (i.e., BCL2, BCL2L1, BCL2L2) of antiapoptotic proteins with demonstrated activity in preclinical ovarian cancer models, including an ex vivo model of 25 high-grade serous ovarian cancers." (PMID 38610999, 2024). "In gastric and ovarian cancers, ISA can inhibit PI3K/Akt signaling, leading to lowered ratio of Bcl-2 to Bax that facilitates apoptosis." (PMID 39376605, 2024). "Our data suggest that HOXB9 overexpression may cause chemoresistance in ovarian cancer cells by differential induction of ERCC-1, MRP-2, and XIAP depending on the strength of HOXB9 expression through inhibition of the mitochondrial pathway of apoptosis, including Bax/Bcl-2." (PMID 36674764, 2023). "The co-cultured ovarian cancer cells show increased expression of PD-L1, VEGF, STAT3, IL-10, IL-6, B-cell lymphoma 2 (BCL2), and MDR1." (PMID 36757936, 2023). "Our previous studies have shown that by also regulating the BAX/BCL2 genes, CAPE can influence the severity of apoptosis in serum ovarian cancer." (PMID 37570782, 2023). "Moreover, SFN and EGCG co-administration suppressed the growth of ovarian cancer cells, caused G2/M cell cycle arrest, and induced apoptosis in SKOV3TR-ip2 cells (paclitaxel-resistant ovarian cancer cell line) by increasing the down-regulation of Bcl-2, hTERT, and PARP cleavage." (PMID 37190316, 2023). "For example, LARP1 enhances the stability of BCL2 but attenuates the stability of BIK, leading to the malignant progression of ovarian cancer." (PMID 34890108, 2022). "The miR-15a-3p has been shown to suppress proliferation and migration inhibiting the expression of BCL2 and MCL1 in epithelial cells and restrains the growth and metastasis of ovarian cancer cells by regulating Twist1." (PMID 36012492, 2022). "It has been found that metformin can induce apoptosis in both primary ovarian cancer cells and SKOV-3 cells by downregulating Bcl-2 and Bcl-xL expression and upregulating Bax and Cytochrome c expression." (PMID 36361682, 2022). "BCL2 overexpression reduced the CDDP-induced growth inhibition and apoptosis in SKOV3 human ovarian cancer cells." (PMID 36354566, 2022). "In a preclinical study, the reduction of ABCB1 and BCL-2 proteins via codelivery of siABCB1 and siBCL2, respectively, sensitized paclitaxel- and cisplatin-resistant SKOV3 and A2780 ovarian cancer cells to therapeutics." (PMID 36551731, 2022). "Recent research revealed that overexpression of FTO was accompanied by BCL-2 upregulation, which was consistent with the trend of regulation of BCL-2 by ALKBH5 found in epithelial ovarian cancer (EOC)." (PMID 36517820, 2022). "It has been reported that overexpression of β-hCG (CGB5 gene) in the ovarian cancer cell lines OVCAR-3 and SKOV-3 showed a remarkable decrease in the expression of BCL2, but increased expression of BAX and BIRC5." (PMID 34941061, 2021). "By reversing the Warburg effect, ABT737, a B cell lymphoma (BCL2) inhibitor, promotes H2O2-induced apoptosis and increases the antitumor effect of oxidative stress, sensitizing ovarian cancer cells to chemotherapy." (PMID 34496868, 2021). "Conversely, it has been reported that increased levels of DRP1 induced by ABT737, an inhibitor of antiapoptotic BCL-2/BCL-XL, promote mitochondrial fission, leading to apoptosis and mitophagy in ovarian cancer cells resistant to cisplatin." (PMID 33946271, 2021). "Overall, compared to the acute lymphoid leukemia cell line Jurkat in our previous studies, ovarian cancer cells have about 2–8 times more BCLXL and 8–50 times more MCL1, but much less BCL2." (PMID 34385422, 2021).
ovarian carcinoma (continued). "Treating cisplatin-resistant ovarian cancer cells with HO-4200 and H-4318 decreases the level of STAT3 target proteins: c-myc, Bcl-2, Bcl-xl, survivin and cyclin D1/D2, giving rise to inhibition of cell survival and induction of apoptosis." (PMID 31949487, 2020). "SRT2183 inhibited the growth of ovarian cancer cells, increased the accumulation of BAX, cleaved-caspase 3 and cleaved-PARP, and decreased the level of anti-apoptotic Bcl-2 and Mcl-1." (PMID 33223507, 2020). "In ovarian carcinoma Tan IIA-treated TOV-21G cells, apoptosis was induced through the downregulation of survivin, while the levels of Bax, Bcl-2, and B-cell lymphoma-extra-large (Bcl-xL) remained unaffected." (PMID 36046197, 2020). "The ovarian cancer cell lines: SKOV3, OVCAR3, OV-90, and 3AO and cisplatin-resistant cell line–SKOV3DDP were used; and Bcl-2 expression levels were the highest in SKOV3DDP." (PMID 31766284, 2019). "This was also seen in ovarian cancer that NEAT1 suppressed apoptosis and increased S-phase cell population through regulating Bcl2 that is mediated by miR-34a-5p36." (PMID 30894512, 2019). "The costunolide contained in crude drug number 118 was reported to inhibit cell viability of multidrug-resistant human ovarian cancer OAW42-A cells by activating apoptotic and autophagic pathways via the decreased expression of B-cell lymphoma 2 (Bcl-2)." (PMID 31163644, 2019). "Taken together, these data show the simultaneous blocking of MDR1 and BCL2 genes, which are mediated by siRNA@PLGA NPs, enables to efficiently promote the sensitivity of drugs on MDR ovarian cancer cell lines." (PMID 29760419, 2018). "Taken together, these data indicate that reduction of BIM protein levels can desensitize ovarian cancer cells to the PI3K/mTOR and BCL-2/BCL-XL drug combination and further highlight the critical role of BIM levels in predicting drug sensitivity." (PMID 28848242, 2017). "YSY01A also enhances cisplatin cytotoxicity in cisplatin-resistant ovarian cancer by suppression of NF-κB and STAT3 targeted genes such as bcl-2." (PMID 28883791, 2017). "BCL-2, BCL-XL, MCL-1 and BAX are determinants of apoptosis in response to chemotherapeutic agents, and are variably expressed in ovarian cancers." (PMID 28399108, 2017). "In conclusion, our study identifies a novel molecular mechanism for E2F1, whereby it targets miR-519d to upregulate RhoC, Bcl-2, cyclin D1, survivin, MMP2, MMP9, STAT3 and HuR expression, promoting tumorigenesis and progression in ovarian carcinoma." (PMID 28146423, 2017). "To confirm LARP1 protein interacts with BCL2 and BIK mRNAs, as suggested by the published LARP1 interactome, we performed RNA-immunoprecipitation in OVCAR8 and SKOV3 ovarian cancer cell lines." (PMID 26717985, 2016). "We analyzed the mRNA levels of BCL-2 and BCL-XL in all ovarian cancer cell lines obtained from cancer cell line encyclopedia (CCLE)." (PMID 24523919, 2014). "We then tested the responses of ovarian cancer cell lines to FAK, PI3K/mTOR, and BCL-2/BCL-XL inhibitors either alone or in combination." (PMID 24523919, 2014). "Cisplatin-Fe3O4 magnetic nanoparticles reversed resistance of ovarian carcinoma cell line SKOV3/DDP by 2.2-fold and down-regulated mRNA levels of Bcl-2 and survivin expression with increased cell apoptosis." (PMID 25071577, 2014). "The comparison of Bcl-2 and CA125 levels for the same samples shows efficacy of Bcl-2 as a urinary ovarian cancer biomarker for reliable dual screening with CA125." (PMID 22969352, 2012). "Conversely, a recent study reported that silencing of the ADM gene in HO8910 ovarian cancer cells was accompanied by growth inhibition and chemosensitization through downregulation of ERK and bcl-2 expression." (PMID 22859951, 2012).
ovarian carcinoma (continued). "EGFR is a tyrosine kinase, which is highly expressed in ovarian cancers, and activates the PI3K-MAPK pathway leading to protein kinase-B (PKB) and Bcl-2-phosphorylation." (PMID 22174601, 2011). "Experimental approaches using the ovarian cancer cell line SKOV-3 as a model system suggest various modes of action exerted by HNTMB based on the generation of ROS, caspase activation, Bcl-2 down-regulation, DNA degradation and G2/M phase cell cycle arrest." (PMID 20184758, 2010). "In cell line studies, BCL-2, BAX, as well as novel MEK1 protein levels have strong influence on ovarian cancer response to cisplatin-based chemotherapy." (PMID 12644821, 2003). "The expression of the BCL-2 family proteins, BCL-2, BAX, BCLXLand BAK have been determined in a panel of 12 human ovarian carcinoma cell lines encompassing a wide range in sensitivity to cisplatin." (PMID 10646901, 2000). "Moreover, IL‐8 promotes ovarian cancer cell drug resistance by inducing the expression of MDR1, apoptosis inhibitor genes (Bcl‐2, Bcl‐xL, and XIAP), and by activating the Ras/MEK/ERK and PI3K/Akt signaling pathways." (PMID 40968783, 2026). "In ovarian cancer models, co-treatment with BMX-001 and PTX significantly reduced the cell viability of CAOV2 cells compared to PTX alone and downregulated the expression of BCL2, NF-κB, and IL-1β." (PMID 40872550, 2025). "In ovarian cancer cell lines SKOV-3 and OVCAR-3, Ex-4 induces apoptosis by modulating NF-κB downstream targets, including matrix metalloproteinase-9 (MMP-9), intercellular adhesion molecule-1(ICAM-1), BAX, Bcl-2, and cyclin D." (PMID 40140925, 2025). "The expression of autophagy degradation substrate p62, autophagy marker LC3 and anti-apoptotic protein Bcl2 were detected by Western Blot in stable overexpression and stable knockdown LOC730101 ovarian cancer cells treated with cisplatin and niraparib respectively." (PMID 39695078, 2024). "Moreover, SOX-2 was also found to induce resistance by increasing anti-apoptotic proteins like Bcl-2 and decreasing pro-apoptotic proteins like PUMA/BBC3 in ovarian cancer cells." (PMID 38864530, 2024). "Although artemisinins have been preclinically evaluated in combination with Bcl-2 inhibitors in leukemia and non-small-cell lung cancer cells, the use of artesunate with navitoclax has not been investigated in ovarian cancer." (PMID 38610999, 2024). "Furthermore, a study demonstrated that ABT737, a BCL2 inhibitor, reduces the cisplatin resistance of SKOV3 ovarian cancer cells by modulating Ca2+ signaling." (PMID 38172597, 2024). "Similarly, bcl-2, bcl-xL, c-IAP1, survivin and NF-κB downregulation after genistein use was found in A2780 and C200 ovarian cancer cells." (PMID 36675194, 2023). "The analysis of the expression levels of the BCL2 and c-MYC genes showed a decrease in the transcript level in patients with ovarian cancer compared to the control group (BCL2: 17.46% ± 3.26 vs. 100% ± 8.32; p < 0.05, c-MYC: 37.56% ± 8.16 vs. 100% ± 9.12; p < 0.05)." (PMID 38003498, 2023). "A more recent study used ABT737, a compound that inhibits Bcl-2, to activate SIRT3 expression in ovarian cancer, and the results showed that ABT737 enhanced the sensitivity of ovarian cancer cells to cisplatin due to the overexpression of SIRT3 and the regulation of mitochondrial fission." (PMID 37345199, 2023).
ovarian carcinoma (continued). "In both ovarian cancer cell lines, a significant downregulation of the anti-apoptotic BCL-2 and significant upregulation of cytochrome c and cleaved caspase 9 was observed, corroborating ST09 drug induces intrinsic apoptotic pathway in ovarian cancer cell lines." (PMID 34837026, 2021). "In particular, ABT-737, a non-selective Bcl-2/Bcl-XL inhibitor can actually affect the ER–mitochondrial contact site, thereby enhancing the response to cisplatin in ovarian cancer cells." (PMID 33802602, 2021). "Additionally, exogenously expressing HVEM in primary ovarian cancer cells and OVCAR-3 cells markedly reduced the expression of Bax (pro-apoptotic protein) and significantly increased the expression of Bcl-2 (anti-apoptotic protein)." (PMID 32312328, 2020). "Moreover, knockdown of HVEM significantly decreased the expression of Bcl-2 and increased the expression of Bax in hypoxic OVCAR3 cells and primary ovarian cancer cells; while overexpression of HVEM had the opposite effects." (PMID 32312328, 2020). "Curcumin downregulated the expression of the Bcl-2, while upregulating the expression of Bax and caspase-3 by repressing the PI3K/AKT pathway, leading to cell cycle arrest in G2/M phase and increased apoptosis of ovarian cancer cells." (PMID 32934709, 2020). "Furthermore, the RT‐qPCR results also showed significantly decreased mRNA expression of c‐Myc and Bcl‐2 and increased levels of Bax and caspase‐3 in BBI608‐treated ovarian cancer cells (P < .05)." (PMID 31778258, 2020). "Ovarian cancer cells are not known to have strong expression of Bcl-2 proteins at the time of diagnosis, and these patients initially respond favorably to chemotherapy with a 50–70% response rate." (PMID 31092272, 2019). "Other studies showed that phospho-STAT3 triggered abnormal dimerization of STAT3, increased the expression of anti-apoptotic proteins Bcl2, Bcl-xl, and MMP2/9, and promoted proliferation, survival, and migration/invasion in ovarian cancer, liver cancer and retinoblastoma cells." (PMID 31422383, 2019). "The BAX represent a prognosticindicator of the patients with ovarian cancer and combineevaluation of BAX and BCL-2 may provide additional prognosticsignificance." (PMID 31285648, 2019). "It indicated that MMP9, Bcl2, and caspase 3 may play roles on TRIM52-mediated regulation in ovarian cancer cells invasion, migration, and apoptosis." (PMID 30185771, 2018). "We hypothesized that, as LARP1 acted as a post-transcriptional regulator of the apoptosis players BCL2 and BIK, modulation of LARP1 expression in ovarian cancer cells would affect their survival." (PMID 26717985, 2016). "The analysis of pulchrin A bound with Bcl-2 at the ABT-737 binding site suggests that pulchrin A shares a similar binding motif with ABT-737 in the BH3 domain of Bcl-2 and thus promotes apoptosis in human ovarian cancer cells." (PMID 27136097, 2016). "To determine whether LARP1 could be regulating the stability of BCL2 and BIK transcripts in patient tumours, we evaluated trends in LARP1, BCL2 and BIK transcript abundance in the TCGA ovarian cancer dataset." (PMID 26717985, 2016). "In our initial studies we noted that Bcl-2 is not widely expressed in ovarian cancer cell lines and this has also been observed in clinical samples." (PMID 27080533, 2016). "DCA alone significantly increased the level of Mcl-1 protein (but not Bcl-2 and Bcl-xL proteins) in ovarian cancer cells, which was markedly attenuated by Met." (PMID 27449090, 2016). "Upregulation of BCL2 is a negative prognostic factor in ovarian cancer and induces platinum resistance." (PMID 26717985, 2016). "Meanwhile, the increased Bcl-2 and decreased BAX expression levels in miR-17-5p overexpressed ovarian cancer cells confirm that miR-17-5p decreases the paclitaxel-induced apoptosis of ovarian cancer cells." (PMID 26500892, 2015).